ZNF350-AS1 (ZNF350 antisense RNA 1)
Synonyms: uc002pyc; HCCAT3
Gene: Long non-coding RNA gene on chromosome 19 (51,949,112 to 51,981,374, forward strand). Ensembl gene ENSG00000269235.
Diseases named in the same sentence as ZNF350-AS1 in open-access papers:
ZNF350-AS1 is named in the same sentence as 3 diseases in open-access papers, as found by Europe PMC text mining. Sharing a sentence is not in itself a finding about the gene and the disease. The quoted sentences say what the papers report.
hepatocellular carcinoma (1 paper, 2024). A malignant tumor that arises from hepatocytes. "ZNF350-AS1, known as hepatocellular carcinoma associated transcript 3 (HCCAT3), is a lncRNA which potentially facilitating tumor growth in patients with HBV-related HCC." (PMID 39575240, 2024).
ZNF350-AS1 also shares sentences with these, for which no sentence is quoted: cancer (1 paper); tumor (1).